RNF130 (ring finger protein 130)
Description:
May have a role during the programmed cell death of hematopoietic cells (By similarity). Acts as an E3 ubiquitin-protein ligase.
Synonyms: GP; G1RZFP; GOLIATH; G1RP
Tractability: Antibody: UniProt predicts a signal peptide or a membrane-spanning region. PROTAC: ubiquitination databases record sites on it.
Gene: Protein-coding gene on chromosome 5 (179,911,651 to 180,072,113, reverse strand). Ensembl gene ENSG00000113269.
Subcellular location: Membrane; Cytoplasm
Pathways (Reactome):
Immune System: Antigen processing: Ubiquitination & Proteasome degradation
Gene Ontology:
Molecular function: protein binding; ubiquitin-protein transferase activity; ubiquitin protein ligase activity
Biological process: programmed cell death; ubiquitin-dependent protein catabolic process; protein ubiquitination
Cellular component: cytoplasm; membrane
Genetic constraint (gnomAD): Loss-of-function variants: 14 observed, 28.91 expected, observed/expected ratio (o/e) 0.48, 90% interval 0.32 to 0.76. The upper end of that interval is the gene's LOEUF score, 0.76, which puts it in group 3 of 6, group 1 being the genes least tolerant of losing a copy. Missense variants: 458 observed, 496.25 expected, observed/expected ratio (o/e) 0.92, 90% interval 0.85 to 1. Synonymous variants: 206 observed, 185.97 expected, observed/expected ratio (o/e) 1.11, 90% interval 0.99 to 1.24.
Homologues: Orthologues: dog RNF130 (99% identical), rat Rnf130 (98% identical), macaque RNF130 (93% identical), pig RNF130 (91% identical), chimpanzee RNF130 (91% identical), mouse Rnf130 (91% identical), guinea pig RNF130 (84% identical), tropical clawed frog rnf130 (69% identical), zebrafish rnf130 (60% identical). Paralogues in human: RNF150 (48% identical), RNF149 (36% identical), RNF128 (35% identical), RNF148 (25% identical), RNF133 (24% identical), RNF13 (21% identical), RNF167 (18% identical), ZNRF4 (17% identical), RNF215 (16% identical).
Diseases named in the same sentence as RNF130 in open-access papers:
RNF130 is named in the same sentence as 17 diseases in open-access papers, as found by Europe PMC text mining. Sharing a sentence is not in itself a finding about the gene and the disease. The quoted sentences say what the papers report.
colorectal cancer (2 papers, 2017 to 2023). A primary or metastatic malignant neoplasm that affects the colon or rectum. "Notably, while RNF167is highly expressed in almost all cancers, other ligases like RNF128(thyroid, liver, urothelial, and colorectal), RNF130 (gliomas), orRNF43 (colorectal cancers) show a more selective tissue-associatedexpression pattern in cancer cells." (PMID 37011906, 2023).
pilocytic astrocytoma (2 papers, 2020 to 2022). Pilocytic astrocytoma is a rare subtype of low-grade glioma of the central nervous system characterized by a well circumscribed, often cystic, brain tumor with a discrete mural nodule and long, hair-like projections that extend from the neoplastic astrocytes. "The fusion partner was RNF130, previously reported in ganglioglioma, pilocytic astrocytoma and DNT." (PMID 35836307, 2022). "It is nevertheless important to note that the presented BRAF multiplexed assay is not designed to detect other rare fusions involving BRAF that have been reported in pilocytic astrocytomas including FAM131:BRAF, RNF130:BRAF, CLCN6:BRAF, MKRN1:BRAF, GNAI1:BRAF, and GTF2I:BRAF." (PMID 33282733, 2020).
breast carcinoma (1 paper, 2023). "Similar to NOSIP in pancreatic cancer, Ring Finger Protein 130 (RNF130) was highly expressed in breast invasive carcinoma (BRCA) in TCGA and was also highly expressed in 11 of 12 breast cancer samples in HPA pathology." (PMID 37845222, 2023).
cervical cancer (1 paper, 2022). A primary or metastatic malignant neoplasm involving the cervix. "Four genes were linked to the prognosis of ferroptosis in cervical cancer, namely, RNF130, CA9, DERL3, and VEGFA, which were obtained by univariate Cox regression analysis in the training set." (PMID 35935576, 2022). "However, CA9, DERL3, and VEGFA genes were all upregulated while the opposite was reported for RNF130 in cervical cancer and was linked to unsatisfactory prognosis in the present research." (PMID 35935576, 2022). "The findings obtained from qRT-PCR illustrated that the expression levels of VEGFA, CA9, and DERL3 in cervical cancer specimens were dramatically elevated in contrast with those in normal specimens, whereas the expression levels of RNF130 were lower contrasted to those in normal specimens." (PMID 35935576, 2022). "In the current study, the novel designed model with four genes (RNF130, CA9, DERL3, and VEGFA) yielded high specificity and sensitivity in identifying prognosis in the cervical cancer." (PMID 35935576, 2022).
colon cancer (1 paper, 2018). "Like miR-340 expression, RNF-130 mRNA expression was lower in colon cancer cells than in the normal colon cell line." (PMID 29435169, 2018).
lung carcinoma (1 paper, 2024). "Furthermore, we assessed the RNF130 expression level in five distinct lung cancer cell lines and a normal bronchial epithelial cell line." (PMID 39132146, 2024).
monoclonal gammopathy of undetermined significance (1 paper, 2019). "In primary samples, RNF130/miR-340 methylation was detected in 4 (22.2%) monoclonal gammopathy of undetermined significance, 15 (23.8%) diagnostic myeloma, and 7 (23.3%) relapsed myeloma." (PMID 31064412, 2019).
multiple myeloma (1 paper, 2019). "As a CpG island is present at the promoter region of its host gene, RNF130, we hypothesized that miR-340-5p is an intronic tumor suppressor miRNA epigenetically silenced by RNF130/miR-340 promoter DNA hypermethylation in multiple myeloma." (PMID 31064412, 2019). "As a CpG island is present at the putative promoter region of its host gene, RNF130, we hypothesized that the intronic miR-340-5p is a tumor suppressor miRNA epigenetically silenced by promoter DNA methylation of its host gene in multiple myeloma." (PMID 31064412, 2019).
myeloma (1 paper, 2019). "By MSP, methylation of RNF130/miR-340 was detected in 4 (22.2%) MGUS, 15 (23.8%) diagnostic myeloma, and 7 (23.3%) relapsed myeloma primary bone marrow samples." (PMID 31064412, 2019). "Moreover, methylation of RNF130/miR-340 correlated with shorter OS in newly diagnosed myeloma, similar to CDKN2A and DAPK1 methylation." (PMID 31064412, 2019). "Methylation frequency of RNF130/miR-340 was not significantly different among those consecutive clinical stages of myeloma (MGUS vs. diagnostic myeloma: P = 1.000; diagnostic myeloma vs. relapsed myeloma: P = 1.000)." (PMID 31064412, 2019). "Moreover, we showed low expression of both miR-340-5p and RNF130 in methylated myeloma lines and high expression in unmethylated lines." (PMID 31064412, 2019). "Similarly, when miRNA expression were correlated with gene expression in myeloma cell lines, co-expression of 32 pairs of intronic miRNAs and their host genes were found, including miR-340/RNF130." (PMID 31064412, 2019). "Therefore, it is likely that methylation of RNF130/miR-340 is an early event in the pathogenesis of myeloma, similar to methylation of miR-203 and miR-342." (PMID 31064412, 2019). "Secondly, in primary samples, methylation of RNF130/miR-340 appeared as early as MGUS, at a frequency comparable to that of myeloma at diagnosis and relapsed myeloma." (PMID 31064412, 2019). "By pyrosequencing-confirmed methylation-specific PCR, RNF130/miR-340 was methylated in 8/15 (53.3%) myeloma cell lines but not normal plasma cells." (PMID 31064412, 2019).
pulmonary fibrosis (1 paper, 2025). Chronic progressive interstitial lung disorder characterized by the replacement of the lung tissue by connective tissue, leading to progressive dyspnea, respiratory failure, or right heart failure. "Furthermore, RNF130 prevents pulmonary fibrosis by inhibiting aerobic glycolysis through mediating the ubiquitination of c-myc." (PMID 40413536, 2025).
tumor (5 papers, 2019 to 2024). "Two additional tumours obtained a calibrated score of 0.7 for this methylation class, including one harbouring a RNF130:BRAF fusion." (PMID 35836307, 2022). "The IHC data revealed that the expression of VEGFA, CA9, and DERL3 in CC specimens was more obvious as opposed to that in normal samples, while the expression of RNF130 was decreased in tumor tissues." (PMID 35935576, 2022). "miR-340-5p, localized to 5q35, is embedded in the second intron of its host gene, RNF130, and has been shown to be a tumor suppressor downregulated in several cancers, such as breast cancer, ovarian cancer, and hepatocellular carcinoma." (PMID 31064412, 2019). "Moreover, RNF130 had low expression levels in LC tumor tissues and was found to be correlated with prognosis." (PMID 39132146, 2024).
cancer (2 papers, 2022 to 2023). A tumor composed of atypical neoplastic, often pleomorphic cells that invade other tissues. "Additionally, the overexpression of RNF130 has been identified in numerous cancers while the opposite expression was reported in other cancers." (PMID 35935576, 2022).
RNF130 also shares sentences with these, for which no sentence is quoted: glioma (2 papers); breast invasive carcinoma (1); ganglioglioma (1); heart transplant (1); pancreatic cancer (1).